CD44 (CD44 molecule (IN blood group))
Diseases named in the same sentence as CD44 in open-access papers (continued):
Sharing a sentence is not in itself a finding about the gene and the disease.
prostate carcinoma (continued). "Studies conducted on the PC3 prostate cancer cell line showed that F77, a prostate cancer-specific mAb carried by CD44, induced apoptosis in a CD44-dependent manner." (PMID 38672650, 2024). "By designing and optimizing OPNPsas a targeted delivery system for CD44 in prostate cancer, the targetingeffect of the tumor can be significantly improved, enabling precisetreatment of PCa with PDT." (PMID 38221923, 2024). "CD44 is involved in prostate cancer, and different CD44 isoforms play different roles in tumor progression and stemness." (PMID 38783892, 2024). "In prostate cancer cells, CD44 collaborates with ERBB2 to contribute to the radioresistance of cancer cells via p38 phosphorylation." (PMID 38783892, 2024). "The UniPR1331 ability to reduce the PC3 stem marker CD44 gave us the rationale to investigate the association with CPT and DTX, due to the critical role played by prostate cancer stem cells in chemoresistance." (PMID 37895923, 2023). "Previous studies have reported that CD44 expression is greater in prostate cancer, and involved in cancer cell proliferation, invasion, migration, and drug resistance." (PMID 37476073, 2023). "It has been reported in prostate cancer that integrin αvβ3 and CD44 pathways function in osteoclastogenesis via a RUNX2/Smad5-signaling axis, which provides evidence for RUNX2-related bone destruction in MM." (PMID 36897488, 2023). "On the basis of these findings, we determined the protein expression of the top markers associated with EMT (CD44, ALDH1, Oct-4, TGFB, Nanog, and Sox2) using immunoblotting in all prostate cancer cell lines." (PMID 37476073, 2023). "Considering its association with the establishment of prostate cancer, different strategies, i.e., miRNA (miR-383), have been tested for their ability to restrict tumor initiation in CD44-positive prostate cancer cells." (PMID 37108498, 2023). "An in vitro study highlighted that the inclusion of WNT3A in prostate cancer cells augments Wnt signaling, and significantly increases self-renewal and sphere formation, which is correlated with β-catenin, CD44, and CD133 expression." (PMID 36969009, 2023). "Treatment of the androgen-dependent prostate cancer cell line LNCaP with saffron induced decreased expression of CD44 and Bcl-2; these are hallmarks of apoptosis, which clearly supports saffron’s anti-tumor function via apoptosis." (PMID 38201944, 2023). "Some studies also suggested that CD44 plays a vital role in cancer stemness, specifically in prostate cancer." (PMID 37476073, 2023). "SOX2 is described as the stem cell marker, and it has been detected in various cancer stem cell subpopulations including lung squamous cell carcinoma, medulloblastoma or CD44-positive prostate cancer." (PMID 38132438, 2023). "Our results confirmed that curcumin inhibited both CD44- and CD44+ prostate cancer cells in a dose-dependent manner." (PMID 37663388, 2023). "The IC50 values of curcumin for CD44- and CD44+ prostate cancer cells were 40.30±2.32 μM and 83.31±2.91 μM, respectively." (PMID 37663388, 2023). "We obtained the most promising results when we investigated the combination of UniPR1331 with cisplatin, due to the ability of UniPR1331 to reduce the PC3 stem marker CD44 and the well-known role of prostate cancer stem cells in chemoresistance." (PMID 37895923, 2023). "We also identified high levels of expression (4.07-fold upregulation) of EMP1 in our aggressive prostate cancer subtypes which regulates the expression of CD44 to promote stemness." (PMID 37476073, 2023). "We found that curcumin significantly increases the expressions of miR-383-5p in both CD44+ and CD44- prostate cancer cells." (PMID 37663388, 2023).
prostate carcinoma (continued). "There was expression variation of each EMT marker among all ARLow/mCRPC/NEPC prostate cancer subtypes, for example, CD44 expression was greater in PC3 and PC3M compared with DU145 (Fig. 1BII–IV)." (PMID 37476073, 2023). "Downregulation of CD44 at mRNA and protein during prostatic cancer progression results in high tumor grade, aneuploidy, and tumor metastasis." (PMID 37461792, 2023). "The genes related to the proliferation, regeneration, and differentiation of stem cells, such as Sox2, OCT3/4, SMO, and β-catenin, were highly expressed in CD44+ prostate cancer cell." (PMID 35342431, 2022). "In prostate cancer, previous study shows that miR-34a is a key negative regulator of CD44+ prostate cancer cells and establishes a strong rationale for developing miR-34a as a novel therapeutic agent against prostate CSCs." (PMID 35715760, 2022). "For example, the levels of CD44 expression increased in cells originating from high-grade prostate cancer compared to CD44 levels found in normal prostate epithelial cells." (PMID 35457063, 2022). "Other studies showed that CD44 and CD133 were associated with high Nanog expression in prostate carcinoma cell lines." (PMID 35800367, 2022). "In prostate cancer, an intracellular form of CD44—released upon extracellular domain cleavage—is transported into the nucleus, where it can bind to RUNX2 leading to its activation and subsequent increased MMPs expression." (PMID 35538545, 2022). "In the case of prostate cancer, they are related to the selective survival of CD44-positive stem-like cells and to the further propagation of their DCX-(hyper)resistant progenies." (PMID 36355492, 2022). "Neither did DCX/FF-treatment upregulate Cx43 in these cells (not shown), even though it has previously been shown to trigger an expansion of super-resistant and invasive prostate cancer cell lineages from CD44+ cells." (PMID 36401206, 2022). "We evaluated the effect of FKA on prostate tumor spheroid formation by prostate cancer stem cells, which were sorted out from CD44+/CD133+ prostate cancer cells 22Rv1 and DU145." (PMID 35912174, 2022). "The ICG-lorded HA nanoagents have showed the prominent value in detecting prostate cancer and CD44-positive cervical cancer." (PMID 36590281, 2022). "Human prostate cancer PC-3 cells displayed high CD44+/CD133+ CSC-like features including enhanced tumor sphere formation and elevated Nanog levels." (PMID 35800367, 2022). "One of the best-studied CSC populations is the CD44+/hi population, which has been widely reported in solid tumors including cancers of the prostate, breast, pancreas, head and neck, and ovary." (PMID 34045601, 2021). "We measured the proportion of primary prostate cancer-derived 22Rv-1 cells that simultaneously expressed that surface markers CD44 and CD133, which have been shown to contain the enriched CSCs in PAC." (PMID 34136381, 2021). "CSCs are distinguished through biomarker combinations, such as CD44+/CD24 for prostate cancer stem cells and triple-negative breast cancer stem cells." (PMID 33981532, 2021). "It accelerates the inhibition of prostate cancer cell marker CD44 in vivo and in vitro and also downregulates the hedgehog-Gli1 pathway that contributes to the anticancer stem cell effect of genistein in prostate cancer TCs." (PMID 34336089, 2021). "Previous studies have also shown that prostate cancer cells express elevated levels of CD44, and CD44 has shown promise as a target for cancer cell therapy." (PMID 33557143, 2021). "Apigenin was also reported to sensitize human CD44+ prostate cancer stem cells to cisplatin therapy by inhibition of cancer stem cells of the lung." (PMID 34884848, 2021). "Previous studies reported the role of TGF-β/SMAD signalling in inducing both stemness markers and EMT in prostate cancer cells by post-transcriptional modification of CD44." (PMID 35201514, 2021).
prostate carcinoma (continued). "It has been reported that CD44 signaling rapidly stimulates integrin α5 and β1 expression and activation in breast and prostate cancer cells." (PMID 34944101, 2021). "Studies regarding CSC markers in prostate cancer are ongoing and CD44 and CD24 are promising candidates." (PMID 34206049, 2021). "Consistently, there is evidence showing that miR-34a antagomirs promote metastasis in CD44- prostate cancer cells, suggesting that downregulation of miR-34a in cancer stem cells contributes to metastasis via regulation of CD44 expression." (PMID 33673143, 2021). "Our previous study demonstrated that a CD44+ subpopulation isolated from PCa cells or tumours possesses both stem cell properties and metastatic potential, serving as metastatic prostate cancer stem cells (mPCSCs) in PCa metastasis." (PMID 34247196, 2021). "In this context, it has been reported that ZEB1 regulates the CSC population of prostate cancer, also characterized by CD44 expression." (PMID 34502091, 2021). "Previously in prostate cancer (PCa) cells, 4-MU was found to inhibit HA synthesis and receptor–mediated signaling, while addition of HA to PC3-ML prostate cancer cells blocked 4-MU-mediated downregulation of CD44, pAKT, and PI3K activity." (PMID 33958632, 2021). "In prostate cancer, CD44 promotes migration and invasion of cancer cells through Hippo-Yap signaling." (PMID 34439211, 2021). "In prostate cancer, miR-34c-3p negatively regulates CD44 and inhibits tumor regeneration and metastasis." (PMID 35004298, 2021). "An increased expression of miR-34a in CD44+ prostate cancer cells prohibited prostate cancer metastasis." (PMID 32117705, 2020). "In the present study, we evaluated CD44 protein and mRNA expression in cell lysates and exosomes isolated from docetaxel-resistant prostate cancer PC-3R cells and parental PC-3 cells." (PMID 32642575, 2020). "The rationale behind this study was a previous report demonstrating that CD44 can raise Sox2 expression in prostate cancer cells." (PMID 33228022, 2020). "Packaged nanoparticles with miR-34a can downregulate the level of CD44 marker of CSCs in a mouse model of prostate cancer." (PMID 33362856, 2020). "In prostate cancer, YTHDC1 regulates CD44 alternative splicing, which is associated with carcinogenesis." (PMID 32808488, 2020). "CD44, a marker for prostate cancer stem cells, is reportedly suppressed by miR-141/200/429, thus prostate cancer samples and cell lines with high CD44 feature very low levels of miR-141/-200/-429." (PMID 32645914, 2020). "To assess the impact of miR-4287 over-expression in prostate cancer cells, we evaluated the RNA expression of CD44 in PC3 and LNCaP cells transfected with miR-CON or miR-4287." (PMID 33473254, 2020). "Our results demonstrate the potential therapeutic value of CIK-based immunotherapy targeting the EpCAM+ and CD44+ prostate cancer cells or PCSCs." (PMID 32183880, 2020). "First, we examined CD44 protein and mRNA expression in cell lysates and exosomes isolated from docetaxel-resistant and -sensitive prostate cancer cells." (PMID 32642575, 2020). "Previous studies and the present one from our laboratory have shown that CD44 is an important regulator of tumor progression in prostate cancer." (PMID 33062960, 2020). "Application of HA-coated or CD44 antibody-coated nanoparticles or liposomes is utilized for specific delivery of chemotherapeutic drugs or bioactive compounds targeting the CD44+ prostate cancer cells." (PMID 32183880, 2020). "Treatment of CD44+/CD133+ human prostate cancer stem cells isolated from populations of DU-145 and 22Rv1 cells with curcumin resulted in reduced cell-cycle progression (Ccnd1 and Cdk4) and stem-cell marker (Oct4, CD44, and CD133) gene expression." (PMID 33182828, 2020).
prostate carcinoma (continued). "Since CD44 has been reported to play critical roles in cancer stemness and prostate cancer metastasis and SLUG is an EMT mediator, we propose that frequent loss of miR-4287 promotes PCa EMT, stemness and metastasis via its regulation of CD44 and SLUG." (PMID 33473254, 2020). "Goksel and colleagues 48 revealed that FRAT1 expression is significantly upregulated in CD133+ CD44+ prostate cancer stem cells and FRAT1 overexpression activates Wnt/β-catenin signaling pathway by inducing β-catenin/TCF activity." (PMID 32201513, 2020). "We previously reported that CD44 is regulated by miR-383, a chr8p miRNA, and miR-708 in prostate cancer." (PMID 33473254, 2020). "MiR-548c-3p overexpression has been mainly detected in a CD133+α2β1Hi CD44+ prostate cancer subpopulation, and exhibits stem cell properties, while it is associated with induction of stem cell-related genes, self-renewal, and radioresistance." (PMID 32932969, 2020). "CD133 is a particularly attractive candidate since elevated expression of this cancer stem cell marker and CD44 has been detected in prostate carcinomas, even though the clinical significance of this observation needs to be further elucidated." (PMID 33335914, 2020). "In this study, we used flow cytometry to isolate CD44+/CD133+/NANOG+ PCSCs from DU145 prostate cancer cells." (PMID 33336042, 2020). "CD44 is characterized as a PCSC biomarker and isolated CD44+ prostate cancer cells from various sources show higher tumorigenicity and metastatic potentials." (PMID 32183880, 2020). "To further validate our immunoblotting findings, we compared the expression levels of CD44s and CD44-ICD in prostate cancer tissue microarrays." (PMID 33062960, 2020). "We have previously shown the expression levels of CD44 in different prostate cancer cell lines including LNCaP, DU145, PC3, and PCa2b." (PMID 33062960, 2020). "Molecular studies showed that CD44+ prostate cancer cells possess stemness characteristics and retain specific intrinsic properties of progenitor cells." (PMID 31315262, 2019). "In several types of cancers, including prostate cancer, CD44 is also a known marker of cancer stem cells (CSCs) or cancer-initiating cells." (PMID 31331331, 2019). "A higher level of CD44 expression was observed in 42% of prostate cancers, 57% of HGPIN and 42% of BPH, while in the case of CD133 expression." (PMID 31366128, 2019). "NANOG expression in prostate cancer was particularly evident at the level of a progenitor/stem CD44+ tumor compartment." (PMID 31366128, 2019). "CD44 is a transmembrane adhesion molecule whose expression is increased in lymphoma cases, whereas its decreased expression is an indicator of prostate cancer progression/metastasis." (PMID 31288785, 2019). "COL4A2 is highly expressed in CD133+/CD44+ prostate cancer spheroids; Head and neck CSCs grown on type IV collagen-coated plates grow much faster than in suspension and maintain CSC traits." (PMID 31334229, 2019). "Activation of c-met in prostate cancer cells stimulates the expression of a stem cell program, characterized by upregulation of CD49b, CD49f, CD44, and SOX9, and downregulation of CD24." (PMID 31366128, 2019). "Using cellular experiments and orthotopic tumor models, we showed that CD44+ prostate cancer cells have CSC-like properties, enhanced epithelial–mesenchymal transition (EMT), and a more immunosuppressive microenvironment." (PMID 31315262, 2019). "Preclinical results have indicated satisfactory efficacies of anti-CD44 therapy among several cancers, including prostate cancer, pancreatic cancer, and gastric cancer." (PMID 30631039, 2019). "Since CD44 was shown to be a direct target of miR-34a it becomes evident that the low expression of this miRNA in prostate cancer stem cells." (PMID 31366128, 2019). "Among the isolated populations from primary prostate cancers, only CD44+ CD133+ cells display in vitro self-renewal and express core stem cell genes OCT4, NANOG, SOX2, nestin, and c-kit." (PMID 31878027, 2019).
prostate carcinoma (continued). "Particularly, the study of prostate cancer tissue in patients undergoing ADT showed that after therapy in the tumoral tissue an increase of CD133+/CD44+/CK5+ cells was observed, concomitantly with a decrease of CK8+ cells." (PMID 31366128, 2019). "Lastly, we showed an inverse relationship between Skp2 expression and CD44+CD24− cancer stem-like subpopulation, suggesting that Skp2 is a promising marker for prostate cancer susceptibility." (PMID 30952903, 2019). "To examine the role of CD44 in tumor behavior, we isolated overexpressed CD44 subpopulations of cells (CD44+ cells) from murine prostate cancer cell lines using flow cytometry and cell sorting." (PMID 31315262, 2019). "It is of interest to note that CD44 positivity was repeatedly reported as one of the properties of prostate cancer cells possessing properties of tumor-initiating cells." (PMID 31366128, 2019). "Quercetin and midkine (MK) siRNA significantly suppressed the survival of PC3 androgen independent prostate cancer cells, androgen dependent LNCaP prostate cancer cells, and CD44+/CD133+ stem cell." (PMID 31261749, 2019). "For example, Quercetin synergizes with epigallocatechin gallate, another popyphenolic compound, to suppress sphere-forming potential of CD44+/CD133+ prostate cancer cells." (PMID 31480735, 2019). "In immunocompetent mouse models, we showed that blockade of IL-6 in prostate cancer cells significantly attenuated IL-6 signaling, decreased the expression of CD44, and attenuated the immunosuppressive tumor microenvironment." (PMID 31315262, 2019). "Knock-down of CD44 photocopied miR-34a overexpression by inhibiting prostate cancer regeneration and metastasis." (PMID 29747682, 2018). "We developed an ELISA using both a CD44 antibody and F77 to identify the special form of glycosylated CD44 from prostate cancer cells as well as from serum samples of prostate cancer patients." (PMID 29423071, 2018). "By contrast, Patrawala et al8 showed that high CD44 expression was found on tumorigenic and metastatic progenitor prostate cancer cells in vivo." (PMID 29236307, 2018). "Prostate cancer stem-like cells (PCSCs) are not only enriched in the CD44+PSA−/lo subpopulation but also employ androgen-independent signaling mechanisms for survival." (PMID 29386546, 2018). "A separate study showed that silencing CD44v9 using short hairpin RNA inhibited assembly of p-Met, AR, HSP90, P110α/PI3K, and CD44 into lipid raft-like structures and reversed the assembly of these components in the complex in prostate cancer." (PMID 29747682, 2018). "In prostate cancer, infection of lenti-miR34a in CD44-positive Du145 cells completely blocked tumor development." (PMID 29747682, 2018). "Functional studies in both pancreatic and prostate cancer identified that CD44 was a direct and functional target of miR-34a." (PMID 29747682, 2018). "Several studies have shown dysregulated CD44 expression in the majority of human cancers, including prostate cancer (PCa)." (PMID 29236307, 2018). "As shown in our previous study, F77 is highly specific to prostate cancer, and the current study indicates that F77 recognizes a special glycosylated form of CD44, CD44v10 at the exon 14 region." (PMID 29423071, 2018). "By immunoprecipitation and mass spectrometry, previous studies identified CD13, CD44, Na+/K+ ATPase, and cytoskeleton proteins as proteins that expressed the antigen for the prostate cancer-specific mAb F77." (PMID 29423071, 2018). "Data from literature described CD44-positive cells as stem-like and more tumourigenic cells in prostate cancer." (PMID 30112117, 2018). "Since we have identified the specific region that harbors the glycosylation sites, a much more specific diagnostic assay can be developed to monitor the special glycosylated form of CD44 during prostate cancer progression." (PMID 29423071, 2018). "F77-glycosylated CD44 was also detected in pre-prostatectomy sera from 22 men with Gleason score 7 prostate cancer." (PMID 29423071, 2018).